INS (insulin)
Diseases named in the same sentence as INS in open-access papers (continued):
Sharing a sentence is not in itself a finding about the gene and the disease.
type 2 diabetes (continued). "The parameters representing insulin resistance, glucagon secretion and suppression for an individual with normoglycaemia obtained from previously published work were evolved over a period of 20 years to the mean values observed in type 2 diabetes." (PMID 40924110, 2025). "Caffeic acid, a hydroxycinnamic compound, has been reported to mitigate type 2 diabetes by improving glucose uptake, insulin secretion, and antioxidant activity, catechin exhibited 58.8% inhibition of α-glucosidase activity, significantly exceeding the effect of acarbose (36.6% inhibition)." (PMID 41226209, 2025). "In this study, M. charantia led to a significant reduction in FBG, HbA1c, insulin, and HOMA, IR, suggesting it may improve insulin sensitivity in patients living with prediabetes and type 2 diabetes." (PMID 41280283, 2025). "While PPARγ agonists are known to enhance insulin sensitivity and aid in managing type 2 diabetes, their clinical use is often restricted due to significant side effects, including an increased risk of heart failure, weight gain, bone fragility, edema, and cancer." (PMID 40286240, 2025). "She had an abundance of concomitant diseases: long-term arterial hypertension, ischemic heart disease, three coronary stent placements, COPD, bronchial asthma, and long-term type II diabetes mellitus, which were treated with sulfonylureas and a combination of insulin and a GLP-1 agonist." (PMID 40429823, 2025). "Moreover, these individuals demonstrate lower fasting glucose levels, improved insulin sensitivity, and a decreased likelihood of developing type 2 diabetes." (PMID 40652248, 2025). "Supporting this observation, individuals with specific genetic variations in genes targeted by LDL-C-lowering therapies (e.g. HMGCR, NPC1L1, PCSK9) exhibit impaired insulin sensitivity and a greater propensity to develop type 2 diabetes, particularly those with impaired glucose tolerance." (PMID 40088285, 2025). "ii) For type 2 diabetes: Insulin may be necessary for a large number of individuals with type 2 diabetes." (PMID 39563945, 2025). "The decrease in weight and BMI in people with type 2 diabetes on a low-carbohydrate diet may increase insulin sensitivity in this group and thus lead to improved glycaemic control." (PMID 41007496, 2025). "In the present study, we investigated whether insulin’s ability to reduce plasma BCAAs is compromised in obesity and type 2 diabetes." (PMID 40404819, 2025). "Consequently, DPP-4 inhibition promotes insulin secretion and prevents the onset of type 2 diabetes." (PMID 41517158, 2025). "If cortisol and/or aldosterone levels are related to insulin secretion and/or resistance in patients with type 2 diabetes, these two hormones might represent novel therapeutic targets." (PMID 40296149, 2025). "Additionally, FFAR4 has been implicated in the control of glucose metabolism, with some studies suggesting its potential to improve insulin sensitivity and prevent metabolic disorders such as type 2 diabetes." (PMID 40807354, 2025). "Furthermore, fasting glucose and urinary sodium are related to type 2 diabetes and hypertension, conditions in which vitamin D reportedly influences insulin secretion, sensitivity, and β-cell function while exerting anti-inflammatory effects." (PMID 40004947, 2025). "Thiazolidinediones are insulin sensitizers and have been used as medication for type 2 diabetes." (PMID 40733606, 2025). "Those with type 2 diabetes required insulin therapy for 8.5 ± 6.9 years." (PMID 38613227, 2025). "The proportion of patients with a diagnosis of type 2 diabetes who were treated with insulin increased from 8.9% in 2012–2013 to 37% in 2018–2019 and 31% in 2020–2021, and the proportion treated with oral agents increased from 51% in 2012–2013 to 57% in 2020–2021." (PMID 39503771, 2025).
type 2 diabetes (continued). "Experimental models of type 2 diabetes, induced by high-fat diets and streptozotocin, revealed that triple therapy significantly improved glucose metabolism by reducing insulin resistance and enhancing insulin sensitivity." (PMID 41394924, 2025). "This chronic inflammation impairs insulin signaling and drives metabolic disorders including type 2 diabetes mellitus (T2DM), hypertension, atherosclerosis, and metabolic dysfunction-associated steatotic liver disease (MASLD), formerly known as nonalcoholic fatty liver disease (NAFLD)." (PMID 40697664, 2025). "Conversely, Type 2 diabetes (T2D) is marked by insulin resistance and defective insulin secretion." (PMID 41497311, 2025). "It is proposed that the total flavonoids could enhance the secretion of insulin secretion from pancreatic islet β-cells in mice with type 2 diabetes." (PMID 40276535, 2025). "Glucagon-like peptide-1 receptor agonists, primarily used as a treatment for type 2 diabetes, improve glucose metabolism by stimulating pancreatic insulin secretion, inhibiting glucagon release, increasing glucose uptake in muscle and adipose tissue, and suppressing hepatic gluconeogenesis." (PMID 40429740, 2025). "The daytime time in tight range measures can complement traditional markers like HbA1c, offering a more comprehensive view of glycaemic variations during dietary weight loss programmes for individuals with prediabetes and type 2 diabetes not on insulin." (PMID 40460001, 2025). "Similarly, metformin is used primarily for the treatment of type-2 diabetes through several mechanisms, including decreasing glucose production in the liver and intestinal absorption, as well as increasing insulin sensitivity." (PMID 40564412, 2025). "Second the glucose-lowering strategies used in the ACCORD study (primarily sulfonylureas and insulin) differed from current strategies for managing blood glucose in patients with type 2 diabetes, which increasingly utilize SGLT2 inhibitors and GLP-1 receptor agonists." (PMID 40674363, 2025). "In study III, we investigated whether 10 weeks of endurance exercise training affected insulin’s ability to suppress plasma BCAAs in individuals with type 2 diabetes and glucose-tolerant individuals with obesity." (PMID 40404819, 2025). "Type 2 diabetes is an immensely common disorder in the human population, characterized by the pancreatic β-cells losing their functionality and the development of resistance to insulin in specific target tissues." (PMID 40284169, 2025). "Thus, this study has provided new insights into the nuclear metabolic adaptations to training in individuals with type 2 diabetes, though the mechanisms behind the improvement in insulin sensitivity remain elusive." (PMID 40413649, 2025). "In a randomized, double‐blind, placebo‐controlled study (n = 81 with type 2 diabetes), a 4‐week intervention with 10 g/day broccoli sprout powder (225 μmol sulforaphane) resulted in improved fasting serum insulin and insulin resistance by 18.2% and 14.2%, respectively." (PMID 40375391, 2025). "It should be noted that the constants of activation and inhibition of insulin reactions (k1_act, k2_act, k4_act, k6_inh) in patients with type 2 diabetes were significantly lower than in healthy individuals, which can be correlated with the state of insulin resistance characteristic of this disease." (PMID 41465237, 2025). "Furthermore, both in adults with type 2 diabetes treated with multiple daily injections and adults with type 2 diabetes treated with basal insulin, the reductions in HbA1c are positively correlated with the HbA1c at baseline." (PMID 39460755, 2025). "Moreover, as they progress from standard glucose tolerance to impaired fasting blood glucose and type 2 diabetes, insulin production declines more rapidly in Africans than in Europeans." (PMID 40643164, 2025).
type 2 diabetes (continued). "Similarly, metabolomic disorders such as Type 2 diabetes are associated with higher alanine concentrations compared to non‐diabetics individuals, which may be beneficial due to its potential to enhance both oxidative and non‐oxidative glucose metabolism, as well as stimulate insulin secretion." (PMID 40501124, 2025). "At the same time, 11 of the 13 mapped genes overlapped with reported genes from previous methylome-wide association studies for association with cardiometabolic traits or diseases, including type 2 diabetes, ischemic heart disease, body mass index, waist circumference, and fasting insulin." (PMID 40176173, 2025). "While the mechanisms of occurrence of these varied phenotypes are not fully understood, alterations in Ado-directed purinergic signaling are likely to lead to phenotypes such as autoimmune-like presentations and insulin-independent type II diabetes that rely on normal Ado signaling." (PMID 40316019, 2025). "The model implies that the cycle could be stopped or prevented by restoring muscle insulin uptake and glucose homeostasis and drugs currently used to treat type 2 diabetes may be of interest for the treatment and prevention of sarcopenia." (PMID 39612082, 2025). "Indeed, islets from individuals with type 2 diabetes fail to respond to IL-1β with insulin secretion, whereas islets from healthy donors are reactive to IL-1β." (PMID 39496966, 2025). "Considering the high-carbohydrate feeding mimicked in our experiment, such metabolic interference at the organism level could potentially contribute to glucotoxicity, insulin resistance, and type 2 diabetes." (PMID 41373668, 2025). "Moreover, impaired glucose stimulated insulin secretion in G3BP1−/− cells is concordant with evidence of G3BP1 downregulation in islets of patients with type 2 diabetes, who suffer from reduced insulin release." (PMID 40355555, 2025). "In the current study, metformin showed successful antidiabetic activity in rats; metformin is recognized for its efficacy in reducing blood glucose levels in individuals with type 2 diabetes; this is mainly achieved by suppressing hepatic gluconeogenesis and enhancing peripheral insulin sensitivity." (PMID 40509282, 2025). "Some studies suggest that clinical intervention with 25(OH)D may improve insulin sensitivity and reduce inflammation in individuals with obesity or type 2 diabetes." (PMID 40149699, 2025). "Previously, the coexpression of insulin and glucagon was observed only in a small proportion of islet cells in nondiabetic subjects, and some increase in the number of such cells was detected in persons with type 2 diabetes." (PMID 39860066, 2025). "In vitro structure–function studies have proposed mechanisms by which SLC30A8 LoF directly affects zinc-mediated insulin storage, processing and secretion, suggesting a possible path to type 2 diabetes treatment that is independent of weight loss." (PMID 41020949, 2025). "Moreover, another RCT demonstrated that 6-month TRE (20 h fasting on three nonconsecutive days per week) yielded greater improvements in glycated hemoglobin and insulin sensitivity in type 2 diabetes patients compared to traditional CR." (PMID 41536827, 2025). "However, high glycemic diets have detrimental metabolic effects, with the most pronounced impact seen in insulin-resistant conditions such as type 2 diabetes (T2DM) or during pregnancy." (PMID 41004024, 2025). "Additionally, fetuin B is elevated in type 2 diabetes and regulates glucose metabolism independently of insulin, which leads to impaired glucose tolerance." (PMID 39858445, 2025). "Conversely, excessive visceral fat promotes chronic low-grade inflammation through increased pro-inflammatory adipokine production, impairing insulin sensitivity, accelerating atherosclerosis, and elevating risks of cardiovascular disease, type 2 diabetes, and specific cancers." (PMID 40860487, 2025).
type 2 diabetes (continued). "Moreover, overexpression of Cav-3 in liver improves insulin sensitivity, insulin receptor signaling and glucose metabolism with increased glycogen synthesis in KKAy mice with type 2 diabetes." (PMID 40012041, 2025). "Obesity is a major comorbidity of type 2 diabetes, and certain glucose-lowering drugs (e.g., insulin, sulfonylureas) may induce weight gain." (PMID 40509444, 2025). "Thus, the GV-high group was enriched for type 1 diabetes and insulin-treated type 2 diabetes, whereas the GV-low group was dominated by type 2 diabetes managed with oral therapy." (PMID 41156463, 2025). "The ability of BRI to predict type 2 diabetes and cardiovascular risk stems from its accuracy in estimating visceral adiposity, which produces adipokines and inflammatory cytokines such as TNF-α, IL-6, and resistin, which impair insulin signaling pathways." (PMID 40727914, 2025). "The therapeutic relevance of targeting these enzymes is further supported by studies indicating that controlling the rate of carbohydrate hydrolysis and glucose absorption can significantly improve glycemic control and insulin sensitivity in patients with type 2 diabetes mellitus (T2DM)." (PMID 40805672, 2025). "Additionally, a randomized controlled trial revealed that a combination of flavan-3-ols and isoflavones enhanced insulin sensitivity and lipoprotein profiles compared to placebo, further lowering the estimated 10-year CVD risk in women with type 2 diabetes." (PMID 39995417, 2025). "Conversely, following the HIIT intervention, insulin-mediated changes in plasma BCAAs were similar in individuals with type 2 diabetes and lean individuals (p=0.463), but reduced in individuals with type 2 diabetes compared with glucose-tolerant individuals with obesity (p=0.038)." (PMID 40404819, 2025). "In addition to cognitive benefits, resistance training has been associated with improved metabolic outcomes in patients with type 2 diabetes, such as enhanced insulin sensitivity and better glycemic control." (PMID 40863572, 2025). "The results of randomized controlled trials generally indicate that red meat intake, or beef specifically, has no impact on potential mechanisms that increase risk of type 2 diabetes, such as reduced insulin sensitivity." (PMID 41377490, 2025). "Similarly, individuals with type 2 diabetes demonstrate reduced insulin-stimulated rates of mitochondrial ATP production in muscles." (PMID 40806527, 2025). "Catabolic pressures may be greater in type 1 diabetes or poorly controlled type 2 diabetes, where insulin dosing variability and appetite disturbances destabilize energy availability." (PMID 41305580, 2025). "Consequently, various strategies have been investigated to boost the activity of these hormones as a potential therapeutic approach to enhance insulin sensitivity and glycemic control in patients with type 2 diabetes." (PMID 40862756, 2025). "Type 2 diabetes is a chronic metabolic disease characterised by impaired pancreatic islet insulin secretion and production, and peripheral insulin-stimulated glucose uptake (‘insulin action’)." (PMID 39404845, 2025). "miR-125b-5p enhances insulin sensitivity and pancreatic β-cell function in type 2 diabetes." (PMID 40016734, 2025). "However, we observed that the parameter governing maximal insulin secretion (k9) was higher for patients with type 2 diabetes than for healthy individuals, a finding consistent with experimental data showing higher insulin peaks in this population." (PMID 41465237, 2025). "A study published in 2023 analyzed whether IF was safe and feasible in people with type 2 diabetes treated with insulin." (PMID 40901288, 2025). "However, the molecular mechanism of how insulin controls glucose transport across membranes and its relationship to impaired glycemic control in type 2 diabetes remains poorly understood." (PMID 40426925, 2025).
type 2 diabetes (continued). "In Wang’s study on an animal model of spontaneous type II diabetes, it was found that AA (25 mg·kg−1) treatment attenuated fasting blood glucose levels in GK rats, and serum insulin levels were also reduced by 70% compared to the control group, which ameliorated insulin resistance to some extent." (PMID 41011581, 2025). "Early short‐term intensive insulin therapy may induce sustained glycemic remission in type 2 diabetes." (PMID 40747755, 2025). "Additionally, after HIIT, plasma BCAA levels in the insulin-stimulated state were significantly higher in participants with type 2 diabetes compared with lean participants (265±16 vs 214±8 pmol/l, p=0.036)." (PMID 40404819, 2025). "Although the avian pancreas does produce insulin, and the avian liver is sensitive to it, it has been proposed that birds are largely insulin-resistant (akin to Type II diabetes), with very limited insulin-mediated glucose uptake in fat and skeletal muscle tissue, and a paucity of insulin receptors." (PMID 39973199, 2025). "As type 2 diabetes progresses, early initiation of insulin may be necessary when oral therapies are insufficient." (PMID 41008502, 2025). "Unfortunately, there are still no medicine that effectively deals directly with the insulin metabolic dysfunction, which is the cause of diabetes, including diabetes mellitus type II." (PMID 39752479, 2025). "Such market forces may have wider impacts on the availability and affordability of insulin for both type 1 and type 2 diabetes." (PMID 40245017, 2025). "Gene association studies have so far identified 16 candidate loci involved in PCOS, including genes involved in gonadotropin action (LHCGR and FSHR), metabolism and sexual development (ESR1), insulin signaling and type 2 diabetes (INSR, THADA, HMGA2) or cell proliferation (YAP1 and SUMO1P1)." (PMID 40551954, 2025). "Thus, the higher pancreatic β‐cell function observed in those with MORN chronotype is clinically important since prior work shows that declines in insulin secretion capacity are a stronger determinant of type 2 diabetes than insulin sensitivity." (PMID 40018087, 2025). "If patients with type 2 diabetes who have higher cortisol levels experience psychological stress, care, such as mental health interventions, may reduce cortisol levels and restore insulin secretion." (PMID 40296149, 2025). "In addition, CCK-1R activation in the pancreas promotes insulin release and improves postprandial glucose control by potentiating glucose-mediated insulin secretion in type 2 diabetes." (PMID 40723884, 2025). "In turn, Hyperglycemia induced increased insulin secretion, establishing a vicious cycle that could exacerbate or precipitate type 2 diabetes." (PMID 40786628, 2025). "Type 2 diabetes accounts for 90–95% of all diabetic patients, and its common pathogenesis is an unhealthy diet, which disrupts the balance between gastrointestinal carbohydrates and insulin secretion and action." (PMID 39942723, 2025). "In subtypes such as HNF1A-, HNF4A-, HNF1B-, and ABCC8-MODY, the primary defect involves impaired coupling of glucose sensing to insulin secretion in pancreatic β-cells, a mechanism that differs fundamentally from the insulin resistance typical of type 2 diabetes." (PMID 41262822, 2025). "Protein tyrosine phosphatase 1B (PTP1B) is a soluble enzyme that plays an essential role in the regulation of metabolism, specifically in the modulation of leptin and insulin sensitivity, marking it as an interesting therapeutic target for the treatment of type 2 diabetes and obesity." (PMID 40906363, 2025). "The anorectic properties of LEAP2 might be very helpful in type 2 diabetes as this hormone might also affect insulin production." (PMID 39796232, 2025). "Peptides from goat milk were shown to enhance insulin sensitivity and help treat type 2 diabetes." (PMID 39974530, 2025).